ABCB1 (ATP binding cassette subfamily B member 1)
Diseases named in the same sentence as ABCB1 in open-access papers (continued):
Sharing a sentence is not in itself a finding about the gene and the disease.
colon carcinoma (95 papers, 2007 to 2026). "Overexpression of NFIB in colon carcinoma Caco-2/TC7 cells caused significant NFIB-dependent inhibition of ABCB1 and ABCG2 gene expression." (PMID 40554316, 2025). "Acquired multidrug resistance (MDR) in colon cancer is associated with a variety of factors, and the overexpression of ATP-binding cassette subfamily B member 1 (ABCB1/P-gp) has been shown to be the crucial regulator of cancer progression." (PMID 39574478, 2024). "The level of the ABCB1 gene encoding MDR1 was much higher in colon cancer cells than in the prostate cells." (PMID 39683740, 2024). "Particularly, AURKA, which is associated to colon cancer and was recently found to be over expressed also in hematological malignancies, as well as the drug resistant associated genes ABCB1, XRCC1 and CBR3 turned out to be affected." (PMID 35836575, 2022). "Patients’ primary colon cancer tumours shown to express the same mut β-catenin allele also expressed high ABCB1 levels." (PMID 22460269, 2012). "We first noticed that citarinostat was significantly more cytotoxic to the parental human KB-3-1 epidermal cancer cells and the parental human S1 colon cancer cells than to the respective ABCB1-overexpressing variant KB-V-1 (R.F = 15) and ABCG2-overexpressing variant S1-M1-80 (R.F = 21) cells." (PMID 33807514, 2021). "A previous study has investigated the relationships between ABCG2, ABCC1, and ABCB1 genes in two different colon cancer cell lines (Caco-2 and HT-29)." (PMID 41557172, 2026). "Lusichelin B exhibited cytotoxicity against colon carcinoma cells while reversingmultidrug resistance via ABCB1 efflux pump modulation." (PMID 40398867, 2025). "Overall, the study indicates that IIF outperformed ATRA in inhibiting cell proliferation and promoting apoptosis, alongside a clear downregulation of ABCB1 protein expression in MDR colon cancer cells." (PMID 41303640, 2025). "In this study, we primarily focused on evaluating the effect of 1C on the protein and gene expression of ABCB1 in colon cancer cells, as well as on studying its possible molecular interaction potential with this transporter." (PMID 40362377, 2025). "Due to the overexpression of the ABCB1 drug efflux pump, common chemotherapeutic drugs can be excreted by P-gp, leading to decreased chemotherapeutic efficacy and high drug resistance in colon cancer." (PMID 39574478, 2024). "Overexpression of ABCB1 inducing multidrug resistance (MDR) desensitizes colon cancer cells to chemotherapy drugs with ABCB1 substrate specificity, resulting from enhanced stability of ABCB1 transcript via IGF2BP3 reading its m6A region." (PMID 37280679, 2023). "Several studies have also been conducted to determine the impact of chalcones on ABCB1, as well as the reversal of drug resistance in colon cancer." (PMID 36983038, 2023). "Several proteins involved in drug efflux belonging to ABC family transporters: ABCB1 (P-glycoprotein-Pgp), ABCC1 (MDR-associated protein 1-MRP1), and ABCG2 (breast cancer resistance protein-BCRP) are increased in colon cancer." (PMID 36009495, 2022). "Other TKIs targeting the ErbB receptor family, specifically allitinib, dacomitinib, vandetanib and AZ5104, did not sensitize cells to paclitaxel treatment in our model despite previous reports of ABCB1 inhibition by dacomitinib in colon cancer cell lines." (PMID 34347777, 2021). "DEHP and MEHP induced the activation of MDR1/ABCB1, resulting in multidrug resistance in colon cancer." (PMID 34208283, 2021). "In this study, the growth curves obtained from MCTSs also revealed a slightly slower growth rate and less invasive expansion in MDR colon tumor spheroids led by ABCB1 silencing." (PMID 34977876, 2021).
colon carcinoma (continued). "In fact, the overexpression of the caudal-related homeobox transcription factor (Cdx2) has been reported to upregulate the expression of ABCB1/gene and consequently P-glycoprotein in highly resistant colon carcinoma to chemotherapy." (PMID 32426274, 2020). "Under physiological conditions, ABCB1 is expressed at relatively low levels in the parent colon cancer cells compared to those in the drug resistant cell lines." (PMID 33163405, 2020). "The expression of the ABCB1 transporter has been reported to vary in colon cancer patients depending upon the chemotherapeutic regimen." (PMID 33163405, 2020). "In this study, we determined the efficacy of poziotinib to overcome ABCG2- or ABCB1-mediated MDR in colon cancer cells and in HEK293 cells." (PMID 33158067, 2020). "The ABCB1-overexpressing SW620/Ad300 colon cancer cells were significantly resistant to paclitaxel (RF = 77.30) and doxorubicin (RF = 74.76) compared to the parental SW620 colon cancer cells that do not express the ABCB1 transporter." (PMID 33158067, 2020). "In the present in vitro study, we report that poziotinib can reverse MDR in colon cancer cells by antagonizing the efflux function of the ABCB1 and ABCG2 transporters, as well as decreasing the expression of the ABCG2 transporter protein." (PMID 33158067, 2020). "The intercellular transfer of ABCB1 was also observed between GFP-expressing drug-sensitive human colon carcinoma cells S1 and KBv200 cells." (PMID 31830995, 2019). "Alongside this, it was revealed that long-term TNF-α treatment reduces the Pgp/ABCB1 transcript and protein levels in intrinsically Pgp-positive colon cancer cells, promoting sensitivity to chemotherapeutic drugs and, possibly, MDR reversal." (PMID 31137684, 2019). "In summary, our data confirmed that Twist1 plays a vital role in MDR of colon carcinoma by upregulating ABCB1 and ABCC1." (PMID 28881781, 2017). "Our study demonstrated that Twist1 can induce MDR in colon carcinoma by promoting the expression of ABCB1 and ABCC1 in vitro and in vivo." (PMID 28881781, 2017). "Firstly, we used drug-resistant colon cancer cells that overexpressed ABCB1, LoVo/ADR, and HCT8/ADR as models." (PMID 28624793, 2017). "We also evaluated the levels of CD133, a colon cancer stem cell marker that tends to accumulate in cell protrusions, and ABCB1/P-glycoprotein (PgP), which pumps out various anticancer drugs including DXR." (PMID 28094304, 2017). "This study is the first to report the selective reversal of ABCB1-mediated MDR by BU in colon cancer." (PMID 28624793, 2017). "We have recently reported that vatalanib, an orally active small molecule multi-tyrosine kinase inhibitor, can sensitize multidrug resistant (MDR) colon cancer cells to chemotherapy under hypoxia by inhibiting two MDR transporters ABCB1 and ABCG2." (PMID 27014726, 2016). "The ABCB1-overexpressing human colon cancer cells SW620/Ad300 showed much higher IC50 values to ABCB1 substrates paclitaxel and vincristine than parental SW620 cells did." (PMID 26296969, 2015). "Colon cancer patients with mutant β-catenin had higher ABCB1 expression, and Wnt signaling was activated in a chemotherapy-resistant side-population (SP) of colon cancer cells." (PMID 25401518, 2014). "We investigated the relevance of mut β-catenin with respect to ABCB1 expression levels to clinical cancer with surgical samples of primary colon carcinomas." (PMID 22460269, 2012). "To assess the impact of gain-of-function β-catenin on ABCB1 and drug resistance and potential response to therapy in colon cancer cells we screened a mechanistically diverse library of anticancer drugs and prototype compounds." (PMID 22460269, 2012). "The positive correlation of expression of β-catenin and ABCB1 was also shown in side-population colon cancer cells, however, ABCG2 expression was also found to be dependent on β-catenin levels." (PMID 22460269, 2012).
colon carcinoma (continued). "For instance, ABCB1 gene was overexpressed in SW620 colon carcinoma and CEM-Bcl2 cells exposed to TSA, or KU812 and NB4 cells exposed to depsipeptide." (PMID 17667922, 2007). "Several carotenoids (antheraxanthin, fetoxanthin, lutein, luteoxanthin, neoxanthin, violaxanthin, violeoxanthin and β-cryptoxanthin) were evaluated for their ability to inhibit efflux activity in colon cancer Colo 320 cell line expressing both ABCB1 and lung resistance protein (LRP)." (PMID 41303640, 2025). "For instance, PXR has been shown to regulate ABCB1 expression in human colon cancer LS174T cells through direct binding to the direct repeat separated by four base pairs (DR4) motif within the ABCB1 promoter region, and thus PXR ligand rifampin induces ABCB1 expression." (PMID 39114355, 2024). "The endocrine disruptor DEHP activated MDR1/ABCB1 gene expression in colon cancer." (PMID 34208283, 2021). "Additionally, TMPE caused significant increase of accumulation of doxorubicin and ABCB1 substrate, rhodamine 123, inside the resistant colon cancer cells." (PMID 33065997, 2020). "However, in the ABCB1 overexpressing SW620/Ad300 colon cancer cells incubated with vehicle, the efflux of [3H]-paclitaxel was 80, 85 and 95%, respectively." (PMID 33158067, 2020). "Similarly, high ABCB1 expression levels were correlated with the developments of intrinsic drug resistance in colon cancer cell lines to daunorubicin and doxorubicin." (PMID 33158067, 2020). "However, it should be pointed out that the ABCG2 and ABCB1 ATPase was expressed in High Five insect cells, whereas the effects of poziotinib on the resistance to the anticancer drugs were done in colon cancer cells." (PMID 33158067, 2020). "The reversal of MDR in colon cancer cells overexpressing the ABCG2 or ABCB1 transporters could result from poziotinib inhibiting the efflux or transport function." (PMID 33158067, 2020). "The intracellular accumulation of [3H]-paclitaxel was significantly lower in the ABCB1-overexpressing SW620/Ad300 colon cancer cells compared to the parental SW620 cells, indicating that the overexpression of the ABCB1 transporter increases the efflux of the substrate, [3H]-paclitaxel." (PMID 33158067, 2020). "Moreover, the inhibition of NFκB activity sensitizes resistant colon cancer cells through a decreased ABCB1 expression, providing a link between NFκB and resistance to chemotherapy through the regulation of human ABCB1 gene expression." (PMID 23259070, 2012). "Finally, inhibition of MARCKS phosphorylation sensitizes colon cancer cells to doxorubicin or 5-FU-based chemotherapy by decreasing ATP-binding-cassette transporter family member ABCB1 internalization, thereby reducing ABCB1 activity, a major cause of chemotherapy resistance in cancer." (PMID 36230850, 2022). "Interestingly, the expression of ABCB1 gene appears to be regulated in colon carcinoma." (PMID 32426274, 2020). "In addition, we suggest that some of the differences in colon cancer incidence in male and female patients may be due to gender-dependent differences in ABCB1 hormonal modulation determining a different role of the same polymorphism." (PMID 25355168, 2014). "Furthermore, increased ABCB1 expression also correlated with β-catenin in adenomatous polyps from patients with familial adenomatous polyposis as well as in side-population colon cancer cells." (PMID 22460269, 2012). "This study aimed to evaluate the potential effects of agmatine on cell viability, migration, invasion, apoptosis, and the expression of the ABCB1, ABCC1, and ABCG2 genes in the Caco-2 colon cancer cell line." (PMID 41557172, 2026).
colon carcinoma (continued). "The increased expression of ATP-binding cassette (ABC) transporter genes such as ABCB1, ABCC1, and ABCG2, as other CSC-related characteristic is involved in regulation of self-renewal and multidrug resistance in ovarian and colon cancer cell lines." (PMID 33849536, 2021). "Knockout of ABCB1 gene resulted in reversal of MDR against ABCB1 chemotherapeutic drugs, increased intracellular accumulation of [3H]‐paclitaxel accumulation, and decreased drug efflux activity in MDR colon cancer cells." (PMID 34977876, 2021). "In this study, we report that in vitro, poziotinib can antagonize both ABCB1- and ABCG2-mediated MDR at 0.1–0.6 μM in the human colon cancer cell lines, SW620/Ad300 and S1-M1-80." (PMID 33158067, 2020). "In this in vitro study, we determined the reversal efficacy of the epidermal growth factor receptor (EFGR) inhibitor, saptinib, in SW620 and SW720/Ad300 colon cancer cells and HEK293/ABCB1 cells which overexpress the ABCB1 transporter." (PMID 33163405, 2020). "In the presence of vehicle for 0.5, 1 or 2 h, the efflux of the ABCB1 substrate, [3H]-paclitaxel, from SW620 parental colon cancer cells, was 10, 25 and 35%, respectively." (PMID 33158067, 2020). "In these experiments, we determined the reversal effect of poziotinib on the efficacy of specific anticancer drugs in colon cancer cells overexpressing the ABCG2 or ABCB1 transporters and in HEK293 cells transfected with the ABCG2 or ABCB1 gene." (PMID 33158067, 2020). "Overall, our results indicate that, in part, poziotinib reverses MDR in S1-M1-80 and SW620/Ad300 colon cancer cell by inhibiting the efflux of ABCG2 and ABCB1 substrates, respectively." (PMID 33158067, 2020). "Twist1-mediated promotion of ABCB1 and ABCC1 expression levels plays an important role in the drug resistance of colon cancer cells." (PMID 28881781, 2017). "In the two colon cancer cell lines, HCT116 and SW480, the average methylation status of ABCB1 was about 40%." (PMID 27689338, 2016). "The effect of mutant (mut) β-catenin on ABCB1 expression and promoter activity was examined using HCT116 human colon cancer cells and isogenic sublines harbouring gain-of-function or wild-type β-catenin, and patients’ tumours." (PMID 22460269, 2012). "In the hydroxycamptothecin (HCPT) resistant cell line SW1116/HCPT from human colon cancer cell line SW1116, ABCG2 is the major factor for multidrug resistance, other than well-studied ABCB1 or ABCC1." (PMID 22870247, 2012). "Our findings indicate that the major ABC transporters ABCG2, ABCC1, and ABCB1 are not modulated by agmatine treatment in colon cancer cells and do not mediate resistance to agmatine in Caco-2 tumor cells." (PMID 41557172, 2026). "Previous studies have also shown the modulation of ABCB1 and ABCC1 by PUFAs in colon cancer." (PMID 36979758, 2023). "In renal cell carcinoma (RCC) and colon cancer cell lines exhibiting MDR and augmented ABCB1 expression, we have identified PITX2 as a contributor to chemotherapeutic drug resistance through transcriptional upregulation of ABCB1 as well as ABCC1, ABCG2, and the drug uptake transporter, SLC22A3." (PMID 35582031, 2021). "One of the main findings of this study was that in vitro, sapitinib significantly increased the efficacy of the anti-cancer drugs paclitaxel and doxorubicin in SW620/Ad300 colon cancer cells and ABCB1 transfected HEK293/ABCB1 cells, which overexpress ABCB1 transporter." (PMID 33163405, 2020). "Consequently, we used an immunofluorescence assay to determine if poziotinib altered the membrane localization of the ABCG2 and ABCB1 transporters in drug-resistant S1-M1-80 and SW620/Ad300 colon cancer cells, respectively." (PMID 33158067, 2020). "The incubation of parental SW620 colon cancer cells with either 0.1 or 0.6 μM of poziotinib or 0.6 μM of verapamil, an ABCB1 inhibitor, did not significantly affect the efflux of [3H]-paclitaxel." (PMID 33158067, 2020).
colon carcinoma (continued). "This could, in part, explain why poziotinib was more potent in reversing the resistance to the ABCB1 substrates, paclitaxel and doxorubicin, than the ABCG2 substrates, mitoxantrone and SN-38 in the colon cancer cells, although this remains to be elucidated." (PMID 33158067, 2020). "In contrast, the expression of the ABCB1 protein in SW620/Ad300 colon cancer cells was not significantly altered by poziotinib." (PMID 33158067, 2020). "It is possible that poziotinib’s increase in the efficacy of the chemotherapeutic drugs in the drug-resistant colon cancer cells could be due to downregulating the expression level of the ABCG2 and ABCB1 transporter protein." (PMID 33158067, 2020). "Thus, the results indicated that poziotinib is reversing MDR in S1-M1-80 and SW620/Ad300 colon cancer cells by inhibiting the ABCG2 and ABCB1 transporter." (PMID 33158067, 2020). "[3H]-paclitaxel accumulation, as previously reported, was significantly decreased in the ABCB1 overexpressing SW620/Ad300 colon cancer cells compared to the non-drug resistant parental SW620 colon cancer cells." (PMID 33158067, 2020). "ABCB1 and ABCA2 display inverse regulation upon the differentiation of colon tumors." (PMID 31417399, 2019). "Here, we found that the expression of ABCB1/MDR1 protein was lost in the inflamed mucosa of UC patients with or without colon cancer." (PMID 28686677, 2017). "Staining for ABCB1 was also diminished in inflamed mucosae in most tissue samples (15 out of 18) from active UC patients without colon cancer." (PMID 28686677, 2017). "It has been reported that in the colon carcinoma cell line SW620, the histone deacetylase inhibitor (iHDAC) trichostatin A (TSA), induces an increase in ABCB1 transcription through the inverted CCAAT box element, with the requirement of the NF-Y transcription factor." (PMID 22846052, 2012). "In ABCB1-overexpressing SW620/Ad300 colon cancer cells, poziotinib also produce a concentration-dependent increase in the efficacy of paclitaxel and doxorubicin in the SW620/Ad300 but not in the SW620 parental colon cancer cells and its efficacy was greater than verapamil, an ABCB1 inhibitor." (PMID 33158067, 2020). "In addition, expression of ABCB1 transporter is increased in colon cancer stem cells due to lack of miR-451 posttranscriptional downregulation resulting in resistance to irinotecan treatment." (PMID 29967761, 2018). "However, the compound has not demonstrated significant intrinsic cytotoxic effects on any of the tested human colon cancer cells and has not been found to sensitize cells to doxorubicin, indicating that efflux by ABCB1 is not the only mechanism of resistance in these cells." (PMID 36983038, 2023). "In addition, sapatinib, in SW620 and SW620/Ad300 cell lines, reversed resistance to a similar magnitude as the ABCB1 transporter substrate, irinotecan, an anticancer drug used to treat colon cancer, whereas oxaliplatin, which is not an ABCB1 substrate, did not produce a significant effect." (PMID 33163405, 2020). "An alteration in the membrane localization of the ABCG2 and ABCB1 transporters (i.e., the transporters would not be located in the cell cytoplasmic membrane and thus can not efflux the anticancer drugs from the colon cancer cells) could decrease the resistance to the anticancer drugs." (PMID 33158067, 2020).